NOD2 (nucleotide binding oligomerization domain containing 2)
Diseases named in the same sentence as NOD2 in open-access papers (continued):
Sharing a sentence is not in itself a finding about the gene and the disease.
Sepsis (continued). "Peritoneal F4/80+Ly-6G− macrophages minimally expressed CD55 and CR1/2 in WT and Nod2−/− mice with CLP, suggesting that expression modulation of these molecules on macrophages minimally contributes to NOD2-mediated C5a generation during sepsis." (PMID 23675299, 2013). "In contrast to protective role in single bacterial infections, NOD2-mediated signals aggravate polymicrobial sepsis." (PMID 23675299, 2013). "Upon SB203580 injection, WT mice exhibited reduced RIP2 expression and phosphorylation, and P38 phosphorylation in total peritoneal cells and serum and peritoneal IL-1β, IL-10, and C5a levels during sepsis, whereas these were unaffected in Nod2−/− mice." (PMID 23675299, 2013). "The NOD2 gene was identified as a postsurgical predictor of sepsis." (PMID 39338216, 2024). "Because both Nod1 and Nod2 sense bacterial cell wall components and signal via Rip2 kinase, we investigated whether there was a possible synergy between Nod1 and Nod2 during severe polymicrobial sepsis." (PMID 25084278, 2014). "We also evaluated whether Nod1 or Nod2 is involved in the sequestration of neutrophils in the lung, thus contributing to pulmonary dysfunction during sepsis." (PMID 25084278, 2014). "To evaluate whether Nod1 or Nod2 mRNAs were systemically expressed by leukocytes during severe sepsis, we isolated peripheral blood mononuclear cells (PBMCs) and neutrophils from naïve and septic mice 6 h after CLP." (PMID 25084278, 2014). "Taking this information into consideration, we evaluated whether Nod1 or Nod2 is involved in the recruitment of neutrophils to the site of infection during polymicrobial sepsis." (PMID 25084278, 2014). "In agreement with the results of the neutrophil recruitment assay, the bacterial loads in the peritoneal cavity and the blood were also similar in WT, Nod1- and Nod2-deficient mice 6 h after non-severe and 6, 12 or 24 h after severe sepsis induced by CLP." (PMID 25084278, 2014). "In this work, we demonstrate that in our experimental conditions, differences in the microbiota of WT and Nod1-, Nod2- or Rip2-deficient mice are not responsible for the absence of a phenotype in CLP-induced sepsis." (PMID 25084278, 2014). "Unexpectedly, neutrophil recruitment was similar in WT, Nod1- and Nod2-deficient mice 6 and 12 h after non-severe sepsis induced by CLP (data not shown)." (PMID 25084278, 2014). "The local levels of IL-6 and TNF-α were also similar in WT, Nod1- and Nod2-deficient mice 24 h after severe sepsis induction (data not shown)." (PMID 25084278, 2014). "Next, to determine whether NOD2-mediated IL-1β and IL-10 production plays a critical role in C5a generation during sepsis, we administered rIL-1β or rIL-10 to WT or Nod2−/− mice 4 h or 12 h after CLP, respectively." (PMID 23675299, 2013). "Our results indicate that NOD2-mediated signals enhance C5a generation by suppressing CD55 expression on neutrophils through IL-1β-dependent or IL-1β-independent IL-10 production during polymicrobial sepsis." (PMID 23675299, 2013). "Thus, it is need to be circumspect to develop therapeutic approach for sepsis based on NOD2-mediated C5a regulation pathway." (PMID 23675299, 2013). "Thus, to functionally link the expression of these molecules to NOD2-mediated C5a generation during sepsis, CD55 and CR1/2 expression levels on gated peritoneal F4/80−Ly-6G+ neutrophils and F4/80+Ly-6G− macrophages were measured." (PMID 23675299, 2013). "Thus, to confirm harmful effects of NOD2-mediated C5a generation on sepsis, we injected WT and Nod2−/− mice with recombinant (r)C5a during CLP-induced sepsis." (PMID 23675299, 2013). "Therefore, it is feasible that NOD2-mediated signals induce IL-1β and IL-10 production by immune cells during sepsis." (PMID 23675299, 2013). "Moreover, our experiments and other studies demonstrated that neutrophils were a major subset to produce IL-1β and IL-10 and highly expressed NOD2 during CLP-induced sepsis." (PMID 23675299, 2013).
Sepsis (continued). "To confirm that the absence of a phenotype in Nod1- and Nod2-deficient mice during polymicrobial sepsis was not the consequence of a microbiotic variation in the knockout mice, we inoculated the cecal bacteria isolated from WT mice into the peritoneal cavities of WT, Nod1- and Nod2-deficient mice." (PMID 25084278, 2014). "In addition, we demonstrated that plasma-derived IL-6 levels in Nod1- and Nod2-deficient or WT mice were similar 6, 12 or 24 h after severe sepsis, as well as 6 h after non-severe sepsis induction." (PMID 25084278, 2014). "Thus, we hypothesize that NOD2 regulates C5a generation via crosstalk with the complement system during sepsis." (PMID 23675299, 2013). "However, it remains unclear the mechanism by which NOD2 affects sepsis responses in vivo by regulating C5a generation." (PMID 23675299, 2013). "Therefore, we propose that a novel NOD2-mediated complement cascade regulatory pathway in neutrophils may be a useful therapeutic target for sepsis." (PMID 23675299, 2013). "To address this hypothesis, we investigated whether NOD2 regulates C5a generation during sepsis." (PMID 23675299, 2013). "Therefore, the high mortality of patients during hypo-inflammatory phase of sepsis might be attributable to the effect of IL-10 on both NOD2-mediated C5a generation and immune suppression, which leads to primary and/or secondary hospital-acquired infection." (PMID 23675299, 2013). "Therefore, inhibitors of RIP2 phosphorylation may be effective therapeutic agents against sepsis and NOD2-related immune diseases." (PMID 23675299, 2013). "Furthermore, considering the CD55 expression levels on neutrophils from WT, Il-1r−/−, Il-10−/−, and Nod2−/− mice with CLP, it is conceivable that NOD2-mediated IL-10 production suppresses CD55 expression on peritoneal neutrophils during sepsis in both IL-1β-dependent and IL-1β-independent manners." (PMID 23675299, 2013). "Therefore, we propose a novel NOD2-mediated complement cascade regulatory pathway in sepsis, which may be a useful therapeutic target." (PMID 23675299, 2013). "In patients with sepsis, microglia are activated by bacteria and other pathogens via TLRs (TLR-2, TLR-4, and TLR-9) and nucleotide-binding oligomerization domain 2 (NOD2)." (PMID 40529139, 2025). "This protective mechanism, the GIV•NOD2 axis, operates within the lamina propria across models of acute colitis (DSS induced), chronic inflammation (IBD), and acute systemic infection (sepsis)." (PMID 41321314, 2025). "And the protein levels of NOD2, RIP2 were up-regulated in sepsis mice but down-regulated when H3 was suppressed." (PMID 32432055, 2020). "NOD2 inhibitor NOD-IN-1 and VSIG4-siRNA were used as interventions to further investigate the mechanism of histone H3 on pyroptosis in sepsis." (PMID 32432055, 2020). "It has been recently demonstrated that Nod2 mediates the production of IL-10, which enhances the production of C5a, contributing to an increased mortality rate after CLP-induced sepsis." (PMID 25084278, 2014). "However, it remains unclear whether NOD2 play crucial role in the pathogenesis of sepsis." (PMID 23675299, 2013). "Therefore, the NOD2-mediated IL-1β-IL-10 regulatory loop in neutrophils helps enhancement of C5a generation, which may partially account for the different kinetics of pro- and anti-inflammatory cytokines in sepsis." (PMID 23675299, 2013). "SB203580, a receptor-interacting protein 2 (RIP2) inhibitor downstream of NOD2, reduced C5a generation by enhancing CD55 expression on neutrophils, resulting in attenuation of polymicrobial sepsis." (PMID 23675299, 2013). "Here, we demonstrate that NOD2 enhances C5a generation by IL-10-mediated suppression of CD55 expression on neutrophils, thereby aggravating polymicrobial sepsis." (PMID 23675299, 2013). "However, whether NOD2 regulates C5a generation during sepsis remains to be determined." (PMID 23675299, 2013).
Sepsis (continued). "Indeed, artesunate inhibited TNF-α and IL-6 production in a dose-dependent manner in peritoneal macrophages of the sepsis mouse model via inhibiting the expression of TLR2 and nucleotide-binding oligomerization domain 2 (Nod2) and suppressing NF-κB activation." (PMID 35178460, 2022). "Based on that, we would be tempted to suggest that Nod1 and Nod2 do not play a major role in polymicrobial sepsis, since the absence of them did not alter the survival." (PMID 25084278, 2014). "Collectively, these data indicate that an additive response of Nod1 and Nod2 is not essential in neutrophil recruitment or bacterial control during CLP-induced severe sepsis." (PMID 25084278, 2014). "Altogether, these data suggest that TLRs, but not Nod1 and Nod2, play a major role in the resolution of sepsis due to the establishment of the local response in polymicrobial sepsis." (PMID 25084278, 2014). "Based on our findings, we cannot exclude the roles of Nod1 and Nod2 in sepsis in the absence of major signaling pathways induced by TLR." (PMID 25084278, 2014). "In agreement with the previous data, WT, Nod1- and Nod2-deficient mice showed similar survival rates in CLP-induced non-severe, moderate and severe sepsis." (PMID 25084278, 2014). "By contrast, the whole bacteria observed during CLP-induced sepsis do not activate Nod1 and Nod2, or does it in a weak intensity." (PMID 25084278, 2014). "In this context, it is unusual that the expression of Nod1 and Nod2 was not altered after CLP-induced sepsis." (PMID 25084278, 2014). "In conclusion, our data indicate that Nod1 and Nod2 do not play a major role in the resolution of polymicrobial sepsis in our experimental conditions." (PMID 25084278, 2014). "Here we did not evaluate the role of Nod1 or Nod2 on the eicosanoid and complement production and we cannot explain the apparent discrepancy regarding the involvement of Nod2 in sepsis." (PMID 25084278, 2014). "We demonstrated that, under our experimental conditions, neither Nod1 nor Nod2 was essential to the onset of inflammation at the infection site, analyzed by chemokine production and neutrophil recruitment, during polymicrobial sepsis." (PMID 25084278, 2014). "Taken together, these data suggest that NOD2-mediated IL-1β-dependent and/or IL-1β-independent IL-10 production enhances C5a generation by suppressing CD55 expression on neutrophils, thereby aggravating sepsis." (PMID 23675299, 2013). "Our experiments demonstrated that serum and peritoneal levels of C5a, but not C3a, were lower in Nod2−/− mice than WT mice during sepsis, while Nod2−/− mice showed higher survival rates than did WT mice, which was reversed by administration of rC5a." (PMID 23675299, 2013). "Furthermore, NOD2-mediated IL-1β and IL-10 production also suppressed LPS-mediated cytokine production by peritoneal immune cells during CLP-induced sepsis." (PMID 23675299, 2013). "Subset analysis revealed that F4/80−Ly-6G+ neutrophils and F4/80+Ly-6G− macrophages were major cells infiltrated into peritoneum during sepsis and the numbers of these cells was similar in Nod2−/− and WT mice (data not shown)." (PMID 23675299, 2013). "To investigate whether NOD2 regulates C5a generation during sepsis, we performed CLP in wild-type (WT) and Nod2−/− mice." (PMID 23675299, 2013). "Furthermore, Nod2−/− mice showed lower levels of RIP2 expression and phosphorylation, and P38 phosphorylation in total peritoneal cells during sepsis than did WT mice." (PMID 23675299, 2013). "In conclusion, NOD2-mediated signals increase C5a levels by suppressing CD55 expression on neutrophils via IL-1β-dependent or IL-1β-independent IL-10 production by neutrophils, thereby aggravating sepsis." (PMID 23675299, 2013). "Plasma samples from sepsis patients (defined according to Bone and colleagues), showed a positive signal in the NOD2 transfected system, but did not induce activation in the fsNOD2-transfected system." (PMID 19638210, 2009).
Sepsis (continued). "Because we showed that Nod1/Nod2 signaling was not indispensable for the production of chemokines and neutrophil recruitment to the infection site during polymicrobial sepsis, we investigated the importance of MyD88, the main adaptor protein of the TLR family, in these events." (PMID 25084278, 2014). "Importantly, no alteration was observed in the Nod1 or Nod2 expression levels 6 h after polymicrobial sepsis induction." (PMID 25084278, 2014). "Based on the known roles of Nod1 and Nod2, members of the NLR family, in the induction of an immune response during infection, we investigated whether these receptors were involved in the physiopathology of sepsis." (PMID 25084278, 2014). "Furthermore, we found that NOD2-mediated IL-10 production by neutrophils enhanced C5a generation by suppressing CD55 expression on neutrophils in IL-1β-dependent and/or IL-1β-independent manners, thereby aggravating CLP-induced sepsis." (PMID 23675299, 2013). "However, the altered CD55 expression on neutrophils affected C5a, but not C3a generation in the NOD2-mediated pathogenesis of sepsis, although CD55 inhibits both C3a and C5a convertase." (PMID 23675299, 2013). "Thus, it is questionable how reduced CD55 expression on neutrophils inhibits the generation of C5a rather than C3a, in NOD2-mediated pathogenesis of sepsis." (PMID 23675299, 2013). "This latter observation indicates that the putative inflammatory cytokines present in the plasma of sepsis patients are not in sufficient amounts to activate the luciferase gene, and that the NOD2 transfection system can selectively and specifically detect bacterial NOD2 agonists." (PMID 19638210, 2009). "This set of results indicates that neither Nod1 nor Nod2 is involved in the release of neutrophil chemotactic mediators and, consequently, in the recruitment of neutrophils during CLP-induced sepsis." (PMID 25084278, 2014). "Taken together, these results suggest that Nod1 and Nod2 do not play a role in survival, chemokine production, neutrophil recruitment to the infectious site, or sequestration to the lungs after CLP-induced severe sepsis." (PMID 25084278, 2014). "Altogether, these data show that Nod1, Nod2 and Rip2 are not required for local chemokine production and neutrophil recruitment during CLP-induced sepsis, and they reinforce the importance of MyD88-dependent signaling for initiation of a protective host response." (PMID 25084278, 2014).
breast carcinoma (23 papers, 2013 to 2025). "Subsequently, further studies revealed an association between NOD2 polymorphisms and the risk of various cancers, including breast cancer and ovarian, endometrial, gastric, and laryngeal cancers." (PMID 38755492, 2024). "NOD2 increases the risk of breast cancer, the research showed that the overexpression of NOD2 inhibited cell proliferation and promoted clone formation in three negative breast cancer cell lines." (PMID 32830857, 2020). "The NOD2-rs2066842 variant was associated with decreased breast cancer risk among postmenopausal EA women, and reduced overall risk of ER negative cancers." (PMID 23991131, 2013). "However, across multiple cancer types, including gastric, lung, and breast cancers, NOD2 polymorphisms and altered expression have been associated with an increased cancer risk and poor patient survival." (PMID 40868292, 2025). "In fact, NOD1 and NOD2 have already been associated to increased risk of breast cancer." (PMID 30791886, 2019). "Polymorphisms in NOD2 have been associated with the risk of many cancers, including lymphoma, CRC, gastric cancer, breast cancer, ovarian cancer, lung cancer, and laryngeal cancer." (PMID 40563649, 2025). "In humans, it has been observed that in some solid tumors (e.g., lung cancers, breast cancers, head and neck epithelial cancers), there is a greater expression of NOD1 and NOD2 on tumor cells and greater polymorphism for NOD2." (PMID 34948194, 2021). "We analyzed heat map of PITX1 and NOD2 gene expression in 50 gene QPCR analysis (pam50) to make sure positive co-expression relationship in breast cancer subtypes of TCGA database generated by UCSC Xena tool." (PMID 32830857, 2020). "A number of immune-related molecules have already been associated to the onset and progression of breast cancer, including NOD1 and NOD2, innate immune receptors of bacterial-derived components which activate pro-inflammatory and survival pathways." (PMID 30791886, 2019). "In the present study, we examined the effects of NOD1 and NOD2 overexpression towards the global proteome of breast cancer-derived Hs578T cells." (PMID 30791886, 2019). "Although NOD1 tumor suppressive role is evidenced in ER-dependent tumors, both NOD1 and NOD2 appear to be relevant for the aggressive potential of breast cancer in vitro." (PMID 30837326, 2019). "We have previously shown that overexpression of either NOD1 and NOD2 innate immune receptors impacts cell proliferation and clonogenic potential of the triple negative, breast cancer-derived Hs578T cell line." (PMID 30791886, 2019). "To better delineate this issue, we investigated NOD1 and NOD2 expression in a panel of breast cancer cell lines, as well as their potential impact in breast tumorigenesis based on in vitro assays." (PMID 29615116, 2018). "The mutation of NOD2 can lead to impaired activation of NFKB in vitro and has associated with colorectal, ovarian and breast cancer." (PMID 29158875, 2017). "In addition, we analyzed the impact of NOD1 and NOD2 overexpression in breast cancer, based on cell proliferation and clonogenic assays." (PMID 29615116, 2018). "In order to determine whether NOD1 and/or NOD2 play significant roles in the onset and progression of breast cancer, here we evaluated the expression of NOD1 and NOD2 in a panel of progressively invasive breast cancer-derived cell lineages." (PMID 29615116, 2018). "Contrarily, NOD2 polymorphisms are associated with higher risk of breast cancer, with no tumor suppressor role being reported." (PMID 29615116, 2018). "Furthermore, STF noticeably induced several gene expressions associated with breast cancer anti-estrogen resistance 3 (BCAR3), cluster of differentiation 83 (CD83), nucleotide-binding oligomerization domain containing 2 (NOD2)." (PMID 28068976, 2017). "Genes extracted from the gene expression omic dataset that play key roles in the development of breast cancer are CDCA5, IL17RB, MUC2, NOD2, and NXPH4." (PMID 35205681, 2022).
breast carcinoma (continued). "Based on the results of previous studies, we chose the miR-122 target genes ADAM10, Bcl-w, VEGFC, PKM2, NOD2, IGF1R and NDRG3 to explore the downstream genes in breast cancer." (PMID 29200969, 2017). "Erbin was found to be downregulated in Her2-overexpressing breast cancer cells, can form a complex with NOD2 (the obligate receptor for RIPK2) and work as a negative regulator of its activity." (PMID 29874851, 2018). "Here, we show that NOD1 and NOD2 display variable expression levels in a panel of estrogen receptor-positive and estrogen receptor-negative breast cancer cell lines." (PMID 29615116, 2018). "Based on the qPCR results in the RPPH1 function cell models, we may infer that RPPH1 promoted breast cancer cell proliferation and cell cycle progression through down-regulation of micro-RNA 122 and influence the expression of ADAM10, PKM2, NOD2 and IGF1R genes." (PMID 29200969, 2017). "Although no tumor suppressor activity has been described for NOD2, NOD1 seems to have important tumor suppressor activity in estrogen receptor (ER)-dependent breast cancer, using an SCID mice xenograft model." (PMID 30837326, 2019).